ENSG00000200891
Synonyms: LOC124900295
Gene: Small nucleolar RNA gene on chromosome 10 (87,994,618 to 87,994,695, reverse strand). Ensembl gene ENSG00000200891.
Gene Ontology:
Biological process: RNA processing
Cellular component: nucleolus
Homologues: Orthologues: mouse Gm26224 (69% identical), rat LOC120096384 (64% identical), zebrafish snord74 (64% identical). Paralogues in human: SNORD74B (67% identical).